COL11A1 (collagen type XI alpha 1 chain)
Diseases named in the same sentence as COL11A1 in open-access papers (continued):
Sharing a sentence is not in itself a finding about the gene and the disease.
cancer (continued). "Given the complexity of interactions between cells of the TME, there are significant knowledge gaps in understanding how COL11A1 signaling cross-talks with other signaling pathways and whether this crosstalk can modulate cancer phenotype." (PMID 33668097, 2021). "Discrepancies between study results could be due to differences in cancer types, cell types, or experimental conditions where COL11A1 levels are manipulated." (PMID 33668097, 2021). "Recently, COL11A1 has been proposed as a therapeutic target in cancer." (PMID 34944877, 2021). "We, therefore, propose that targeting ITGA11 and COL11A1 expressing CAFs to block cancer–stroma interactions may serve as a novel, promising anti‐tumor strategy." (PMID 33682233, 2021). "Therefore, COL11A1 is thought to preferentially phosphorylate AktSer473/CREBSer133 to promote cancer cell survival in PDAC." (PMID 33531986, 2021). "The alteration of the TGF-β signaling pathway by the COL11A1 gene indicates that the SMAD4 alteration frequency of 15.5% might drive the formation of cancer." (PMID 33597969, 2021). "We hope that our results will give rise to testable hypotheses that could eventually lead to the development of pan-cancer therapeutics inhibiting the ASC to COL11A1-expressing CAF transition." (PMID 34283835, 2021). "With regard to the structure of COL11A1, it is unknown which two alpha chains assemble with COL11A1 in a cancer setting." (PMID 33668097, 2021). "Taken together, the miRNAs regulation of COL11A1 can be specific to cancer types." (PMID 34944877, 2021). "Among collagen genes, COL11A1 is of notable interest in cancer." (PMID 34584216, 2021). "These may have contributed to further activation of the cancer stroma by the interaction of the infiltrating ITGA11+/ COL11A1+ CAFs with the cancer microenvironment." (PMID 33682233, 2021). "Interestingly, COL11A1 levels are frequently upregulated in various cancers and high levels of COL11A1 are correlated with poor clinical outcome in many solid cancers." (PMID 33668097, 2021). "The COL11A1-expressing CAF signature has been confirmed to be a pan-cancer signature." (PMID 34283835, 2021). "This knowledge will facilitate the development of novel therapies to treat COL11A1-high cancers." (PMID 33668097, 2021). "Therefore, we suggest that the COL11A1/Akt/CREB axis inhibits cancer cell apoptosis by promoting BCL-2 and p-BAXSer184 expression and reducing BAX content." (PMID 33531986, 2021). "It has been shown that COL11A1 promotes survival signaling in other cancer types as well." (PMID 33668097, 2021). "In this review, we discuss how COL11A1 serves as both a biomarker and a key player in cancer." (PMID 33668097, 2021). "However, despite the importance of COL11A1 in skeletal development and fibrillogenesis, its biological functions in cancer remain poorly understood." (PMID 33668097, 2021). "This review will discuss the recent discoveries in the biological functions of COL11A1 in cancer." (PMID 33668097, 2021). "However, regardless of the origin, there is undisputed evidence to link tumor or stromal COL11A1 to cancer invasiveness and metastasis." (PMID 33668097, 2021). "We hypothesized that ITGA11 and COL11A1 may regulate altered CAF phenotypes and could play a role in cancer progression and associated poor prognoses." (PMID 33682233, 2021). "Moreover, in these cancers, the expression of COL11A1 positively correlates with progression and lymph node metastasis." (PMID 33668097, 2021). "Taken together, these findings highlight the role of COL11A1 as a pivotal molecule that regulates cancer aggressiveness and the possible commonality in the deregulation of tissue architecture that drives cancer progression across multiple cancer types." (PMID 33668097, 2021).
cancer (continued). "Collagen type XI alpha 1 (COL11A1), a minor fibrillar collagen crucial for skeletal development and collagen fiber assembly, is a novel biomarker associated with poor survival and chemoresistance in several cancer types including ovarian cancer." (PMID 32312965, 2020). "This might be explained by the evidence that COL11A1 promotes the invasion and migration ability of carcinoma cells and is involved in the formation of metastases." (PMID 32878206, 2020). "In summary, the targeted inhibition of Wnt/β-catenin signaling and COL11A1 (an upregulated gene within integrin signaling pathway) seems to increase the sensitivity to platinum and taxane agents in cancer by deregulating not only Wnt/β-catenin pathway (per se) but also AKT and NF-kB pathways." (PMID 30894224, 2019). "Finally, we evaluated the relationship of SC66 treatment with COL11A1 and revealed a novel mechanism for COL11A1 regulation by SC66 resulting in the sensitization of cancer cells to chemotherapy and the promotion of tumor cell apoptosis in EOC." (PMID 30975980, 2019). "Furthermore, the focal adhesion genes such as COL1A1, COL10A1, and COL11A1 were also found to be up-regulated in the present study and are also reported to be up-regulated in various cancers including breast tumours." (PMID 31292488, 2019). "Recent research has emphasized the role of col11a1 in various cancers." (PMID 29619382, 2018). "These included COL11A1, a minor fibrillar collagen shown to mark activated cancer-associated fibroblasts (CAFs) that is not typically expressed in fibroblasts associated with inflammation and fibrosis." (PMID 29630593, 2018). "Based on these findings, we propose that COL11A1 increases cancer chemosensitivity and could serve as a therapeutic biomarker for EOC." (PMID 26087191, 2015). "Hence stromal changes of collagen XI α-1 (COL11A1) expression are regarded as markers of cancer initiation and progression." (PMID 26579497, 2015). "Given COL11A1’s pro-tumor role, it could become a novel target in cancer immunotherapy." (PMID 40721833, 2025). "COL11A1 may serve as an attractive biomarker to provide new insights into cancer therapeutics." (PMID 38649961, 2024). "In addition, when co-cultured with cancer cells, normal fibroblasts could be stimulated to upregulate COL11A1, and finally facilitate malignant progression." (PMID 38806505, 2024). "Genes PRKCZ (Protein Kinase C Zeta), FGR (Src family protein), KDM4B, MPO, COL11A1, FUT4 (Fucosyltransferase IV), and APEH (acylpeptide hydrolase) are directly associated with tumor aggressiveness, growth, and migration, and invasiveness, resulting in poor clinical outcome in cancer patients." (PMID 38086861, 2023). "Similarly, COL11A1 has also been associated with patient survival in NSCLC and other cancers." (PMID 36404344, 2022). "Therefore, abnormal expression of COL11A1 during cancer development might constitute a specific indicator of neoplastic transformation." (PMID 35327583, 2022). "Also, the proteins bound to the N-terminal and C-terminal domains of COL11A1 in different cancer types are unknown." (PMID 33668097, 2021). "This suggests that COL11A1-rich ECM might increase migration of cancer cells." (PMID 33668097, 2021). "However, how COL11A1 is incorporated into the extracellular matrix and induces cellular signaling in a cancer context is still unknown." (PMID 34638339, 2021). "Furthermore, it has been shown that normal fibroblasts can be “educated” to express COL11A1 by co-culturing them with cancer cell lines, further solidifying the idea that the interplay between cancer cells and fibroblasts is essential for malignant progression." (PMID 33668097, 2021). "Finally, although no study has tested whether integrin α11β1 can bind to COL11A1, the gene expression of integrin subunit α11 has been shown to correlate strongly with COL11A1 gene expression in a number of different cancer studies." (PMID 33668097, 2021).
cancer (continued). "Additionally, ERK1/2 signaling induced ITGA11 and COL11A1 expression in cancer stroma." (PMID 33682233, 2021). "The overexpression of COL11A1 is positively upregulated in the cancer tissue across the various clinicopathological conditions, while negatively regulated in the case of promoter methylation indicating that the hypermethylation can induce the inhibition of cancer development." (PMID 33597969, 2021). "Therefore, we hypothesized that COL11A1 might upregulate fatty acid synthesis to supply cancer cells with fatty acids to promote FAO." (PMID 32312965, 2020). "Mutations in both CSMD3 and COL11A1 are not specific to any one cancer type, and these genes may be accruing mutations due to their long length." (PMID 29141020, 2017). "Single-cell studies identify COL11A1+ CAFs as a chemoresistance-driving subtype in OS, activating IGF-1R/Akt signaling to promote cancer stemness." (PMID 40909292, 2025). "COL11A1 is a crucial element of the ECM across a wide spectrum of cancers, with numerous reports highlighting its involvement in malignant tumor behavior." (PMID 39845732, 2025). "Single-cell studies also identify COL11A1+ CAFs as a chemoresistance-driving subtype in OS, activating IGF-1R/Akt signaling to promote cancer stemness." (PMID 40909292, 2025). "This suggests that the upregulation of COL11A1 and the downregulation of CAV1, CXCL12, and SPTBN1 in the cancer microenvironment led to the downregulation of IL-6 and IL-33." (PMID 40898538, 2025). "Other notable proteins, such as ACKR3, COL11A1, CPA4, and FZD6, were previously reported as potential therapeutic targets in cancer." (PMID 38652547, 2024). "Single-cell analysis revealed that, in aggressive cancers, cells with the ASC/FAP signature convert to a particular type of CAFs expressing COL11A1, THBS2, and INHBA." (PMID 38466528, 2024). "Therefore, the expression of COL11A1 in LUAD may affect the efficacy of cancer immunotherapy." (PMID 38649961, 2024). "Inhibition of constitutively active Wnt/β-catenin signaling in the human ACC cell line, NCI-H295R, significantly reduced the expression of COL11A1 and other ECM components and decreased cancer cell viability." (PMID 37509222, 2023). "We constructed a multi-cancer fibroblast atlas, in which fibroblasts were classified into six clusters: BAMBI+ FBs, CLDN1+ FBs, COL11A1+ FBs, CXCL14+ FBs, DPT+ FBs and RGS5+ FBs." (PMID 36744260, 2023). "Recently, we investigated the role of COL11A1 in inducing CAF activation and its interaction with cancer cells." (PMID 35847935, 2022). "Collagen Type XI Alpha 1 Chain (COL11A1) is a subtype of fibrillar collagen, which was proved to be related to cancer cell proliferation, migration, and tumorigenesis." (PMID 35669376, 2022). "It has been shown that CAFs, which express and secrete COL11A1 into the ECM, promote the proliferation, angiogenesis, invasion, and drug resistance of cancer cells." (PMID 35847935, 2022). "The high expression of COL11A1 also induces the expression of molecules such as Twist1 and MMP3, which are related to drug resistance and invasion of cancer." (PMID 36293285, 2022). "Procollagen 11A1 (COL11A1), the α1 chain of collagen XI, has been found to be consistently upregulated in the ECM of different carcinoma types." (PMID 34378164, 2022). "A couple of studies have shown that COL11A1 activates NFκB signaling, and multiple studies have shown that COL11A1 induces EMT markers and promotes proliferative and migratory phenotypes of cancer cells." (PMID 33668097, 2021). "Specifically, a COL11A1/INHBA/THBS2-expressing gene signature was found to be present only after a particular staging threshold, different in each cancer type, was reached." (PMID 34283835, 2021). "We observed a correlation in miR-335 and COL11A1 levels between tissue samples of 137 patients with EOC and 23 non-cancer controls." (PMID 34944877, 2021).
cancer (continued). "Since then, many research results were published connecting one of the genes COL11A1, INHBA, THBS2 with poor prognosis, invasiveness, metastasis, or resistance to therapy, in various cancer types." (PMID 34283835, 2021). "Among these proteins, the overexpression of MMP14, ITGA2, THBS2, COL1A1, COL3A1, COL11A1 and COL6A3 has been experimentally confirmed in PDAC, while that of COL12A1 and COL5A2 has been shown in other types of cancer." (PMID 34094925, 2021). "This is in line with other studies that demonstrate the role of TGFβ1 signaling in driving COL11A1 expression, EMT phenotype, and cancer invasion and metastasis." (PMID 33668097, 2021). "This leads to further CAFs with specific phenotype: ‘ITGA11+/ COL11A1+ CAF’, through the CAF–cancer cell interaction." (PMID 33682233, 2021). "A pan-cancer gene expression study shows that several genes of COL11A1-correlated gene set are drivers of the metastatic program, EMT, and are co-expressed in COL11A1-expressing CAFs." (PMID 33668097, 2021). "TGF‐β1‐induced fibronectin also resulted in excessive deposition of COL11A1, accompanied by ITGA11 expression in the cancer stroma, resulting in a CAF‐specific phenotype: ITGA11+/ COL11A1+ CAFs." (PMID 33682233, 2021). "We also detected the expression level of COL11A1, integrin α1β1 and DDR2 in cancer cell total lysates by western blotting to assess the knockdown efficiency of si-COL11A1, siα1β1 and siDDR2." (PMID 33531986, 2021). "In this review, we will provide a comprehensive overview of the biological functions of COL11A1 in cancer and discuss how COL11A1 mediates the crosstalk between cancer cells and the tumor microenvironment (TME) to regulate cancer cell phenotype." (PMID 33668097, 2021). "Herein, we showed that COL11A1 is conducted by integrin α1β1 and DDR2 to mediate cancer cell proliferation and activate AktSer473 signal transduction." (PMID 33531986, 2021). "Cancer cell proliferation, invasion, migration, and metastasis were stimulated when CDX2 and let-7b were depleted or COL11A1 was over-expressed." (PMID 31938021, 2020). "COL11A1, COL6A1, MMP2, NID1, and FLT4 have been shown to have a positive role in regulating motility and invasion of various cancer cells." (PMID 28555007, 2017). "By quantifying cancer genome evolution using the gene gravity model, we identified six putative cancer genes (AHNAK, COL11A1, DDX3X, FAT4, STAG2, and SYNE1)." (PMID 26352260, 2015). "Collagen type XI alpha 1 chain (COL11A1) has been shown to promote tumor invasion and metastasis in various malignant tumors; however, its expression regulatory mechanism and biological function in LUAD remain unclear." (PMID 41836251, 2026). "While molecular mechanisms such as COL11A1 upregulation and MDR1-mediated drug efflux play central roles in chemoresistance, clinical and tumor related variables including: age, cancer subtype, and disease stage, also significantly influence therapeutic outcomes." (PMID 41462920, 2025). "Finally, while our study provides valuable insights into the role of COL11A1 in HNSCC, it is essential to consider the broader implications across different types of cancers and diseases." (PMID 40322427, 2025). "In addition, pan-dCAFs expressed high levels of COL11A1, COL1A1, MMP11 and MMP1, which are closely related to cancer invasion." (PMID 38827236, 2024). "In our study, using a single-cell analysis-related database, we found that COL11A1 was mainly expressed by CAFs in the TME rather than from LUAD cancer cells, which was also supported by our results of immunofluorescence." (PMID 38649961, 2024). "COL11A1 may serve as a novel prognostic biomarker and provide new insights into LUAD therapeutics, particularly cancer immunotherapy." (PMID 38649961, 2024). "We identified that the COL11A1+ fibroblasts only exist in various tumor tissues but not in normal tissues, thus we named them cancer-specific fibroblasts (CSFs)." (PMID 36744260, 2023).
cancer (continued). "SC66 has been shown to inhibit the binding of NF-YA and c/ERBβ to COL11A1 promoter, thereby reducing the chemotherapy resistance induced by Twist1 and Mcl-1, and inhibiting the expression of MMP3 and the invasion ability of cancer cells." (PMID 35847935, 2022). "However, previous studies have shown the opposite predictive role of COL11A1 in response to PD1 checkpoint immunotherapy, reconfirming the heterogeneity and complexity of TME in cancers." (PMID 36389832, 2022). "Despite our increased understanding of COL11A1 functions in CAF, it remains unclear whether COL11A1 secreted by cancer cells and CAFs has structural and functional similarities." (PMID 35847935, 2022). "In line with this hypothesis, it was identified that CAFs exhibiting the “metastasis signature” composed of COL11A1, INHBA (inhibin beta A), THBS2 (thrombospondin 2), originate from adipocytes when the cancer metastasizes to a fat-rich microenvironment." (PMID 33668097, 2021). "Interestingly, COL11A1 is not widely overexpressed in cSCCs, at either the mRNA or protein levels, as shown here, raising the possibility that COL11A1 mutations may in fact lead to a less stable protein, as is seen with other cancer mutant proteins." (PMID 34584216, 2021). "Mutant COL11A1, however, has not been characterized in cancer and a functional role for the COL11A1 protein in promoting neoplastic progression to cancerous invasion in tissue has not been studied." (PMID 34584216, 2021). "Although the authors hypothesize that COL11A1 forms a heterotrimer with COL5A2 at a 2:1, other combinations of these collagen alpha chains might be possible in a cancer type-specific manner." (PMID 33668097, 2021). "Finally, we validated our results in other cancer types (head and neck, ovarian, lung, breast), suggesting the pan-cancer nature of the ASC to COL11A1-expressing CAF transition." (PMID 34283835, 2021). "MicroRNAs (miRNAs) are dysregulated in multiple cancers, including epithelial ovarian carcinoma (EOC); however, the regulation of COL11A1 by miRNAs in EOC remains unclear." (PMID 34944877, 2021). "Herein, our study reveals the impact of COL11A1 gene product in the alteration of PTEN, PIK3CA, KRAS, and BRAF which might downregulate the RTK-RAS-PI3K signaling pathways to induce cancer development." (PMID 33597969, 2021). "COL11A1 overexpression has only been observed in desmoplastic areas of the tumors composed majorly of CAFs in different cancers but not in fibroblasts in inflammatory diseases, making COL11A1 a unique marker for CAFs." (PMID 33668097, 2021). "Both ITGA11 and COL11A1 were highly expressed in cancer stroma compared to normal lung tissue and the expression level of ITGA11 correlated with that of COL11A1, suggesting interaction with the cancer stroma." (PMID 33682233, 2021). "Not surprisingly, COL11A1 is one of the four core matrisome proteins upregulated across all cancer types and correlates positively with worst clinical outcome in all cancer types tested." (PMID 33668097, 2021). "Culturing COL11A1-low cells in the presence of COL11A1 extract or CAFs did not induce COL11A1 expression in the cancer cells." (PMID 32312965, 2020). "Further insights may come from cancer-specific fibroblasts, which coexpress COL11A1 and CAF markers that are unique to tumors but absent in healthy tissue." (PMID 40721833, 2025). "Notably, COL11A1+ FBs only existed in various tumor tissues but not normal tissues, thus, we named them cancer-specific fibroblasts (CSFs), while other clusters existed in both tumor tissues and normal tissues." (PMID 36744260, 2023). "Therefore, it is very likely that COL11A1 promotes cancer stemness, although there are no studies yet that have confirmed the role of COL11A1 in cancer stemness." (PMID 33668097, 2021).